CRP (C-reactive protein)
Diseases named in the same sentence as CRP in open-access papers (continued):
Sharing a sentence is not in itself a finding about the gene and the disease.
bipolar disorder (continued). "A significant decrease in CRP was observed in patients admitted to the inpatient unit during the first 7 days of treatment, as their symptoms of bipolar disorder improved." (PMID 34970174, 2021). "We found that patients admitted to the inpatient unit reported a reduction of CRP during the first 7 days of supervised treatment, in synch with the improvement of their acute symptoms of bipolar disorder." (PMID 34970174, 2021). "High levels of CRP have been found in various psychiatric disorders but particularly in schizophrenia, depressive disorders, bipolar disorder." (PMID 34970174, 2021). "This retrospective pilot work aimed to evaluate the relationship between the improvement of the acute symptoms of bipolar disorder and the improvement of the inflammatory marker levels C-reactive protein in hospitalized patients." (PMID 34970174, 2021). "Overall CRP levels are significantly elevated in patients with bipolar disorder compared with controls." (PMID 33672126, 2021). "When the multinomial regression was performed, male gender, diagnosis of bipolar disorder, lower total cholesterol level, and higher CRP serum levels predicted HLSA." (PMID 30881317, 2019). "Only male gender, having a diagnosis of bipolar disorder, lower total cholesterol, and higher CRP serum levels predicted HLSA." (PMID 30881317, 2019). "Several recent studies have investigated the role of C-reactive protein (CRP) in bipolar disorder (BD), but few studies have directly investigated the interaction between CRP genetic variants and peripheral CRP concentration across different phases of BD." (PMID 31788733, 2019). "Only 3/42 subjects were SCID + bipolar depression with 1 and 2 in Low and High CRP-Glu groups, respectively." (PMID 30202011, 2018). "The aim of this study is to explore the changes and clinical significance of serum C3, C4, hypersensitive C-reactive protein (hsCRP) and uric acid (UA) in patients of bipolar disorder (BD)." (PMID 30186190, 2018). "We observed nominal evidence that genetically elevated CRP is causally associated with SBP, DBP, knee osteoarthritis, and bipolar disorder." (PMID 27327646, 2016). "To date, a number of studies have consistently shown that there are elevated C-reactive protein levels in bipolar disorder, both in acute mania and remission." (PMID 25889215, 2015). "Given these associations, it is plausible that variations in the serum levels of BDNF and CRP may correspond to differences in cognitive profiles among individuals with bipolar disorder." (PMID 41367212, 2025). "The two CRP SNPs we focused on in our study, rs3093059 and rs 3093077, have not been previously associated with bipolar disorder based on our literature search." (PMID 37181328, 2023). "However, we found evidence, after outlier correction, for a potential protective effect of bipolar disorder on CRP levels in bidirectional analysis." (PMID 34280516, 2021). "Neurological diseases and bipolar disorders also presented positive genetic correlations with CRP." (PMID 34386016, 2021). "However, “Parkinson's disease,” “microbiota-gut-brain axis,” “microbiome,” “dysbiosis,” “bipolar disorder,” “impact,” “CRP,” and “immune system” were identified as new frontiers of research, whose bursts are currently ongoing." (PMID 33488420, 2020). "The citation burst detection for keywords identified several keywords, including “Parkinson's disease,” “microbiota-gut-brain axis,” “microbiome,” “dysbiosis,” “bipolar disorder,” “impact,” “C reactive protein,” and “immune system,” as new research frontiers, which have currently ongoing bursts." (PMID 33488420, 2020). "In addition, because its effects in bipolar disorder have been validated in studies, reasonable CRP control may also be beneficial." (PMID 34386016, 2021). "In this study, we investigated the clinical and biological differences among cognitive subgroups in patients with bipolar disorder, focusing on the relationship between serum levels of BDNF and CRP." (PMID 41367212, 2025).
bipolar disorder (continued). "She suffered from bipolar disorder, chronic fatigue, memory/concentration problems, and severe joint pain with elevated markers of inflammation (rheumatoid factor, ESR, and CRP)." (PMID 37764145, 2023). "A recent retrospective, observational, cross-sectional study evaluated the differences between elevated CRP levels (i.e., CRP > 3 mg/L and ≤ 10 mg/L) in subjects with MDD, bipolar disorder (BD), and obsessive-compulsive disorder (OCD)." (PMID 35163538, 2022). "This pilot study aimed to evaluate the relationship between C-Reactive-Protein (CRP) and bipolar disorder severity." (PMID 34970174, 2021). "In bipolar disorder, investigations of proinflammatory cytokines, namely, TNF-α, INF-γ, IL-6, and high sensitivity CRP, found elevated levels in a cohort of 30 patients in acute mania as compared to healthy controls." (PMID 29181395, 2017). "Because SED is conceptualized as a transdiagnostic endophenotype among ADHD and major affective disorders, we investigated the effects of both diagnoses (ADHD and major affective disorders) and SED on MMP-9, CRP, and IL-6 levels and on inhibitory control function." (PMID 40219625, 2025). "A meta-analysis of 2161 patients with bipolar disorder and 81 932 healthy controls found that the increase in CRP concentration was specific to bipolar disorder, regardless of symptom severity." (PMID 39283831, 2024). "It remains to be established which specific factor contribute to the decrease in CRP and whether the decrease of CPR is related to an improvement of bipolar disorder symptoms or vice-versa." (PMID 34970174, 2021). "Biomarker meta-analyses suggest a combination of high-sensitivity C-reactive protein/interleukin-6, brain derived neurotrophic factor/tumour necrosis factor (TNF)-α and soluble TNF-α receptor 1 can differentiate specific mood phase in bipolar disorder." (PMID 30113291, 2018). "Meta-analysis showed that CRP levels were increased in bipolar disorder, regardless of mood state." (PMID 33672126, 2021). "Furthermore, no previous causal evidence supported these detected signals (except for the bipolar affective disorders), suggesting heterogeneous and non-repeatable effects of CRP across populations." (PMID 34386016, 2021). "However, no other relationships were found among IL-6, IL-8, and CRP levels and the clinical features of unipolar and bipolar depression." (PMID 30762747, 2019).
dengue (85 papers, 2009 to 2026). "Patients with hyperinflammation (raised CRP and/or ferritin levels) are at highest risk of poor outcomes in dengue." (PMID 39931105, 2024). "Des études ont récemment montré qu'une CRP > 50 mg/l était très évocatrice d'un diagnostic autre que la dengue, comme la leptospirose ou le paludisme." (PMID 37389381, 2023). "Higher CRP levels during early illness in patients with dengue, was shown to associate with an increased risk of progression to severe disease and was also associated with hospitalization." (PMID 37676889, 2023). "In relation to severe dengue, in addition to CRP and AST, SDC-1 and VCAM-1 were also significant associations." (PMID 37838744, 2023). "CRP/SAP as well as TNF-α/IL-1β were independently associated with both dengue severity and overall disease manifestation." (PMID 33436908, 2021). "In particular, we found a significant association of higher levels of CRP with severe dengue fever during the first 3 days of the disease (febrile phase)." (PMID 33436908, 2021). "Previously, we showed that CRP as a single biomarker was useful for early dengue diagnosis and risk identification, which is currently easy to use in all settings." (PMID 34154705, 2021). "This large case-control study has shown that increased CRP levels in the first 3 days of illness are associated with worse dengue clinical outcomes, especially in children." (PMID 32063229, 2020). "Recently, several studies have reported that C-reactive protein (CRP) is positively associated with severe dengue infection, and patients with higher plasma CRP in the initial period of dengue, are at higher risk to develop plasma leakage." (PMID 32414383, 2020). "A number of previous studies have demonstrated the role of CRP in differentiating dengue from specifically bacterial and malarial infections, although the most effective CRP thresholds for predicting underlying etiology remain difficult to define." (PMID 32063229, 2020). "CRP levels of less than 30 mg/L (approximately the median CRP levels in dengue patients) showed that higher CRP levels associated with higher odds of dengue diagnosis (OR for each two times increase in CRP level was 1.28, 95% CI 1.18–1.40)." (PMID 32063229, 2020). "Higher CRP levels in the first 3 days of illness were associated with increased odds of severe or intermediate dengue, after correcting for age, DOI at enrollment, plasma viremia levels, and immune status." (PMID 32063229, 2020). "This is in accord with the previously reported observation that patients with dengue who had plasma loss (a characteristic of severe disease) presented higher levels of CRP." (PMID 30901375, 2019). "In summary, our study highlights single measurement of CRP as a potential useful and simple biomarker to identify patients who are at risk for developing a more severe dengue illness and to help triage patients requiring hospital care." (PMID 26247033, 2015). "Similarly,CRP levels within the first 3 days of illness have been associatedwith a higher risk of progression to severe dengue." (PMID 40165016, 2025). "Our results bolster the limited evidence provided by other cost-effectiveness analyses in south and southeast Asian primary care settings of LF-RDTs which singularly test for enteric fever, dengue, and CRP (or other host biomarker associated with bacterial infection)." (PMID 38523864, 2024). "In conclusion, higher levels of the ten biomarkers (VCAM-1, SDC-1, Ang-2, IL-8, IP-10, IL-1RA, sCD163, sTREM-1, ferritin, and CRP), when considered individually, are associated with increased risk of adverse clinical outcomes in both children and adults with dengue." (PMID 34154705, 2021). "In summary, CRP measured in the first 3 days of illness could be a useful biomarker for early dengue risk prediction and may assist differentiating dengue from other febrile illnesses." (PMID 32063229, 2020).
dengue (continued). "However, in patients with CRP levels ≥ 30 mg/L, higher CRP associated with lower odds of dengue diagnosis (OR for each two times increase in CRP level was 0.64, 95% CI 0.55–0.73)." (PMID 32063229, 2020). "While the mechanism of association between elevated CRP and dengue remains unclear, immune enhancement is a known feature of dengue pathogenesis, and it may be that severity of disease manifestation is determined by overall magnitude of the immune response." (PMID 32063229, 2020). "The risk of DHF/DSS and severe dengue is significantly related to the increasing levels of CRP." (PMID 26247033, 2015). "First, the retrospective nature of this study limits the ability to establish causality between the biomarkers (CRP, PCT, and WBC count) and the severity of dengue." (PMID 40692953, 2025). "Early indicators of severe dengue include laboratory findings such as elevated c-reactive protein (CRP), elevated aspartate aminotransferase (AST), decreased serum albumin, and decreased platelet count." (PMID 39899203, 2025). "When comparing primary and secondary infections, CRP.hs levels were significantly higher in secondary dengue cases (median 9.15 [0.2–295] vs. 3.55 [0.4–192]; p = 0.029), suggesting a more pronounced inflammatory response in these patients." (PMID 40838976, 2025). "Elevated IL-6/CRP corroborates the coagulation–proinflammatory interplay in the immune response in dengue pathogenesis." (PMID 41583452, 2025). "Our findings are consistent with individual studies reporting high CRP concentrations in melioidosis, often exceeding levels observed in other tropical infections such as leptospirosis, dengue, and scrub typhus." (PMID 41010302, 2025). "CRP is also significant in the development of dengue and has the potential to be a predictive biomarker." (PMID 39345300, 2024). "CRP has been identified as a biomarker for differentiating dengue from other febrile illnesses and predicting severe disease." (PMID 38235130, 2023). "High CRP levels were observed in severe dengue patients of >100mg/L in all six DSS patients including 2 fatalities." (PMID 38235130, 2023). "Performance of the C-reactive protein (CRP) cut-off at 50mg/L in differentiating leptospirosis from dengue fever cases at hospital admission on Reunion Island from 2018 to 2019." (PMID 37195992, 2023). "Pathologically, dengue is characterised by high levels of inflammatory markers like CRP, endocan and IL-8." (PMID 36268329, 2022). "We investigated the association of 10 biomarkers (VCAM-1, SDC-1, Ang-2, IL-8, IP-10, IL-1RA, sCD163, sTREM-1, ferritin, CRP) with the development of severe/moderate dengue (S/MD)." (PMID 34154705, 2021). "Our further analysis showed a strong correlation of the plasma Gal-9 levels with prominent mediators of cytokine storm (IL-6, TNF-α, MCP-1, IP-10, and MIP-1α) and CRP as reported in dengue fever." (PMID 33947753, 2021). "In our study, the median CRP level was significantly elevated in people with severe dengue compared with the less severe form (DwoWS/DWWS)." (PMID 33436908, 2021). "Inflammatory APP, such as increased CRP/SAP, has also been significantly associated with decreased platelet counts and increased SGPT in patients with severe dengue." (PMID 33436908, 2021). "Nevertheless, elevated CRP and high pulse rate along with prolonged and high-grade fever in a patient with dengue should be considered as alarming signs for concurrent bacterial infection." (PMID 34507614, 2021). "A high CRP in early illness was suggested to have a good predictive value in developing severe dengue." (PMID 33207759, 2020). "We investigated the value of C-reactive protein (CRP) measured early on illness days 1–3 to predict dengue disease outcome and the difference in CRP levels between dengue and other febrile illnesses (OFI)." (PMID 32063229, 2020). "There were 30 patients in the OFI group and 896 patients in the dengue group who had CRP measurements at follow-up." (PMID 32063229, 2020).
dengue (continued). "We found the median CRP level of approximately 30 mg/L among dengue cases within the first 3 days of illness." (PMID 32063229, 2020). "For each twofold increase in CRP level, the OR (95% CI) of having severe or intermediate dengue was 1.17 (1.07–1.29)." (PMID 32063229, 2020). "Low CRP (< 1.0 mg/dl) is usual in dengue, but elevated CRP (> 3.0 mg/dl) level is found in severe dengue cases." (PMID 32134948, 2020). "After excluding 9 samples with CRP values above the upper range of the assay, data from 1117 patients with laboratory-confirmed dengue and 394 patients with OFI were included in the final analysis." (PMID 32063229, 2020). "CRP levels exceeding >30 mg/L during the first 3 days of illness were shown to be a possible biomarker in predicting the development of severe dengue." (PMID 33207759, 2020). "CRP levels at enrollment in patients with severe or intermediate dengue were higher than in patients with uncomplicated dengue, with median levels (interquartile range) of 34.0 (17.4–71.8 mg/L), and 28.6 mg/L (10.5–58.9 mg/L), respectively." (PMID 32063229, 2020). "For example, uncomplicated cases were chosen to match demographic characteristics of the severe/intermediate group, so the CRP results from these uncomplicated cases cannot be generalized to all uncomplicated dengue cases in the cohort." (PMID 32063229, 2020). "Higher levels of CRP have also been found in patients with dengue compared to other viral illnesses." (PMID 32063229, 2020). "Other studies found similar levels with observed mean CRP levels of 19.0 mg/L on the first day of illness in dengue cases." (PMID 32063229, 2020). "Laboratory findings including full blood count, hepatic transaminases, creatinine, C-reactive protein, and dengue serology were also collected." (PMID 32454916, 2020). "In patients with confirmed dengue, median (interquartile range) of CRP level within the first 3 days was 30.2 mg/L (12.4–61.2 mg/L) (uncomplicated dengue, 28.6 (10.5–58.9); severe or intermediate dengue, 34.0 (17.4–71.8))." (PMID 32063229, 2020). "The next step was to quantify the serum levels of IL-1β, IL-6, IL-18, IL-10, TNF-α and CRP, as indicators of the inflammatory status in the dengue patients." (PMID 30901375, 2019). "While we found a decrease in the expression of inflammasome-related genes in dengue patients, we also found increased levels of the inflammatory marker CRP, and this was higher in DWWS patients, suggesting a residual inflammatory process." (PMID 30901375, 2019). "For dengue, a lower CRP (aOR 0.956, 95%CI 0.927–0.986, p = 0.005) was the only consistently significant predictor variable on multivariate analysis." (PMID 29852003, 2018). "Low CRP in DENV patients has been previously documented with only 4/119 patients having a CRP >50 mg/L, although the same study reported a mild elevation of >5 mg/L CRP in 25% of patients with dengue fever." (PMID 30274405, 2018). "Median CRP level in the dengue cohort (18.2) was significantly lower than the OFI cohort (47.55), p = 0.040." (PMID 29098002, 2017). "In this analysis this would have supported the use of testing for dengue and the use of the CRP test, but less so for the scrub typhus test where overall antimicrobial consumption was either similar to or higher than current practice." (PMID 27027303, 2016). "In the bacterial infection group, higher levels of white blood cell count, C-reactive protein, blood urea nitrogen, creatinine and lower level of hemoglobin was detected compared to the dengue group." (PMID 27240351, 2016). "We model the ability of dengue and scrub typhus rapid tests to inform antibiotic treatment, as compared with testing for elevated C-Reactive Protein (CRP), a biomarker of host-inflammation." (PMID 27027303, 2016). "In total, 80% of patients were classified correctly using the CRP test, compared with 52% based on current practice, 46% using a dengue test, and 59% using scrub typhus test." (PMID 27027303, 2016).